BCL2 (BCL2 apoptosis regulator)
Diseases named in the same sentence as BCL2 in open-access papers (continued):
Sharing a sentence is not in itself a finding about the gene and the disease.
breast carcinoma (continued). "BCL2 amplification/copy number gain is rare and correlation between transcript and protein levels in breast cancer is not linear (unpublished observations), suggesting post-transcriptional regulation." (PMID 20664598, 2010). "Detection of the BCL-2 protein expression level, particularly, combined with the detection of the expression of BCL-2 and BAD as well as ER and PR were helpful in confirming the prognosis of breast carcinoma." (PMID 20691103, 2010). "The expression rates of BCL-2 in youth and menopause human breast carcinoma were 47.5% and 75%(P < 0.05), The expression rates of BAD in youth and menopause human breast carcinoma were 30% and 65%, the differences were statistically significant(P < 0.05) (P < 0.05)." (PMID 20691103, 2010). "These evaluated the role of BCL2 as a predictor of OS or DFS in 5,892 cases of breast cancer." (PMID 18510726, 2008). "Another possible explanation for our findings is that in good-prognosis breast cancer tumors, Bcl-2 and Bag-1 have other dominant roles that are not related to their anti-apoptotic functions." (PMID 18430249, 2008). "Nevertheless, our finding that COX-2 suppression did not suppress Bcl-2 leads us to propose that other mechanisms exist by which celecoxib induces apoptosis, at least in the breast cancer cell lines we tested." (PMID 17612393, 2007). "Relationship between the Bcl-2 and HER2 protein expressions in breast cancer." (PMID 16839413, 2006). "In the present study we showed that treatment with AS Bcl-2 and AS Bcl-xL ODNs produced sequence-specific decreases in protein levels, thereby enhancing the chemosensitivity of BT-474, ZR-75-1, and MDA-MB-231 breast cancer cells to various anticancer drugs both in vitro and in vivo." (PMID 16280040, 2005). "Because tamoxifen was used very widely for early breast cancer in Scotland from the mid-1980s, it was not possible to assemble sufficient unexposed, poor outcome, cases to validate the index based on BCL-2 positivity and presence of carcinoma in situ." (PMID 15138474, 2004). "Unlike Bcl-2, Bcl-XL is highly upregulated in human breast cancer tissues and effective to suppress TRAIL-triggered apoptosis in several tumour cell lines." (PMID 12644829, 2003). "We found differential expression pattern of Bcl-2 and Bcl-XL in the human breast cancer tissues and present evidences for the inhibitory effects of Bcl-XL, but not Bcl-2, on the TRAIL-induced apoptosis of tumour cell lines." (PMID 12644829, 2003). "Western blot and immunohistochemical analyses showed that expression of Bcl-XL, but not Bcl-2, was highly increased in human breast cancer tissues." (PMID 12644829, 2003). "To elucidate the role of bcl-2 and ZOL-induced apoptosis in breast cancer cells, we determined whether forced expression of bcl-2 was capable of abrogating ZOL-induced loss of cell viability and DNA fragmentation." (PMID 11986784, 2002). "In breast cancer (MCF-7), it induces cell cycle arrest at the G2/M cell phase, increases ROS levels and inhibits the PI3K/AKT signaling pathway, thereby promoting apoptosis, and also accelerates apoptotic processes by down-regulating Bcl-2 and up-regulating Bax protein expression [1034]." (PMID 40490812, 2025).
breast carcinoma (continued). "Finally, western blotting was employed to detect the expression of apoptosis‐related protein caspase‐3, cleaved‐caspase‐3, Bcl‐2, Bak, DRP1, and FIS1 to explore the effect of FLT on apoptosis in human breast cancer cells MCF‐7 and MBA‐MB‐231 along with the mechanism." (PMID 40761496, 2025). "Additionally, TRIM25 decreased the protein stability of BRD7 through the ubiquitin proteasome pathway by increasing the K48-linked ubiquitination of BRD7 at the K119 site, and then activated the YB1/Bcl-2 signal axis, thus mediating malignant progression and PTX resistance of breast cancer." (PMID 41315221, 2025). "Both compounds inhibited breast cancer cell growth and induced apoptosis and there was a concordance between the effects of NR4A1 and NR4A2 knockdown and effects of DIM-3,5 analogs in TNBC cells and on several NR4A-regulated genes including EGFR, β1-integrin, bcl-2 and c-Myc." (PMID 41184246, 2025). "Furthermore Bim bound to BCL-2 and favored the apoptosis of MDA-MDB-breast cancer stem cells." (PMID 39859345, 2025). "This set comprised senescence markers (CDKN1A, LMNB1, MKI67), apoptosis regulators (BCL2, BCL2L1), a highly overexpressed gene (ITGB6), and drug targets (ACTA2, GSDMC, KRT6A, PDE1A, PSMA8), all of which showed strong concordance with our RNA-seq data in all four breast cancer cell lines." (PMID 40312750, 2025). "Both compounds inhibited breast cancer cell growth and induced apoptosis and there was a concordance between the effects of NR4A1 and NR4A2 knockdown and effects of DIM-3,5 analogs in MDA-MB-231 cells and on several NR4A-regulated genes including EGFR, β1-integrin, bcl-2 and c-Myc." (PMID 40313760, 2025). "In breast cancer cells, hyperoside has been reported to modulate intracellular ROS levels and inhibit the NF-κB pathway, leading to a decrease in the expression of anti-apoptotic genes such as XIAP and Bcl-2, while promoting the accumulation of Bax, a pro-apoptotic factor." (PMID 40942095, 2025). "Statistical analysis also revealed a positive correlation between BCL-2 expression and the presence of ER and PR receptors, suggesting that BCL-2 may be a marker of favorable prognosis, particularly in hormone-dependent types of breast cancer." (PMID 39685591, 2024). "Finally, miRNA-204-5p was up-regulated in the OCP group; it promotes apoptosis by targeting BCL2 in prostate cells and is a tumor suppressor in breast cancer, and lower levels predict lymph node negative status in endometrial cancers." (PMID 38999962, 2024). "We then compared the distribution of POU2F3-positive cells and cells expressing ER, CK5 (a basal marker), and oncogenes often expressed in tuft cell-like cancers (BCL2 and KIT) to ask whether the POU2F3-positive cells had a phenotype similar to tuft cell-like breast cancers." (PMID 37179317, 2023). "The mechanisms by which Bcl-2 can protect against breast cancer, including its role in apoptosis or whether non-apoptotic functions are involved, are yet to be elucidated and correlated." (PMID 37370761, 2023). "Moreover, we examined the downregulation of Bcl-2 with the silencing of NONO in breast cancer cells." (PMID 37370134, 2023). "In addition, a clinical study reported that Bcl-2 expression was lower in ERβ1-positive breast cancer than in ERβ-negative breast cancer." (PMID 37936981, 2023). "Additionally, in breast cancer cells MCF-7 and MDA-MB-231, Bcl-2 decreased and BAX increased." (PMID 36142874, 2022).
breast carcinoma (continued). "The mechanism of differential Bcl-2 protein expression in breast cancer is not fully elucidated, and understanding the mechanisms regulating Bcl-2 family protein expression in ER+ breast cancer could benefit treatment options." (PMID 35053443, 2022). "However, bCAFs increased Mcl-1 expression in breast cancer cells both at the mRNA and protein level, without affecting Bcl-2 levels." (PMID 35053443, 2022). "The expression of Bcl-2, an anti-apoptotic or pro-survival protein, was markedly decreased in MCF-7 and MDA-MB-231 breast cancer cells following the inhibition of SIRT1 with sirtinol, which indicates that SIRT1 promotes the growth of breast cancer through the upregulation of the Bcl-2 protein." (PMID 36291902, 2022). "The Huaier polysaccharide component SP1 (a type of purified Huaier polysaccharide) could increase the proportion of Bax/Bcl-2 through the MTDH signaling pathway, which could be another potential mechanism of Huaier in apoptosis induction in breast cancer cells." (PMID 35458475, 2022). "This is in line with the analysis of breast cancer cell lines in Cancer Cell Line Encyclopedia data, which highlights a role for both MCL1 and BCL2L1 (BCL-XL) in maintenance of breast cancer cell line viability in 2-D culture, whereas BCL2 appears largely non-essential in this context." (PMID 35349392, 2022). "To assess whether the absence of Bcl-3 altered Bcl-2 expression in mammary tumors as it did during involution, we performed immunoblot for Bcl-2 in different tumor subtypes from bcl-3−/− and control mice." (PMID 35681213, 2022). "Similarly, in solid cancers including rhabdomyosarcoma, breast cancer, SCLC and melanoma, synergistic killing was achieved, either through transcriptional up-regulation of pro-apoptotic BIM, NOXA, PUMA or BMF or suppression of BCL-2 and/or BCL-XL expression." (PMID 34581776, 2021). "Notably, this phenomenon is not restricted to just blood cancers but also extends to solid cancers such as lung, prostate, liver, and breast carcinomas in which high levels of BCL-2 expression is observed even in the absence of BCL-2 gene rearrangements." (PMID 33799592, 2021). "We also predicted that basal-like subtype breast cancer has higher sensitivity to five (bleomycin, daporinad, sepantronium bromide, etoposide, and ICL1100013) of the seven drugs, luminal B subtype breast cancer has higher sensitivity to ABT737 and navitoclax, both of which are BCL2 inhibitors." (PMID 33858332, 2021). "Also, METTL3 was reportedly upregulated in breast cancer cells and tissues, with gene silencing significantly inhibiting cell proliferation and promoting apoptosis by regulating Bcl-2, thereby indicating an oncogenic role for METTL3 in breast cancer progression." (PMID 35096816, 2021). "Indeed miR-34a may affect positively in the modulation of drug sensitivity in breast cancer by suppression of NOTCH1, BCL-2, and CCND1." (PMID 33773546, 2021). "Using the human breast cancer cell lines LCC1 (antiestrogen sensitive) and LCC9 (antiestrogen resistant) we found that either calcitriol or EB1089 lowered phosphorylation of IRE1α, JNK, and Bcl2, especially in LCC9 cells, suggesting that VitD has the potential to inhibit autophagy in these cells." (PMID 34069442, 2021). "The high BCL2 group showed better disease-free survival (p = 0.004) in HRc-positive breast cancers but there was no prognostic significance of BCL2 expression in HRc-negative breast cancers." (PMID 34099764, 2021). "However, BCL2 status did not reveal a significant survival difference in terms of regional recurrence-free survival and contralateral breast cancer-free survival." (PMID 34099764, 2021).
breast carcinoma (continued). "Importantly this compound phenocopied paclitaxel’s ability to sensitize breast cancer cells lines to the BCL-xL inhibitor WEHI-539 but it did not sensitize them to the BCL-2 inhibitor ABT-199." (PMID 31937780, 2020). "Here, we demonstrate that combination treatment, including SM/z-VAD and the BCL2 inhibitor ABT-263 (Navitoclax), results in cancer cytotoxic effects and synergistic effect on the standard chemotherapeutic regimen by phosphorylation of the necrosome complex in YARS-positive breast cancer." (PMID 33239070, 2020). "In solid tumors, including prostate cancer and breast cancer, STAT3 activation which was mediated by IL-6 could enhance the expression of anti-apoptotic proteins, such as BCL2 or survivin which has constantly been regarded as a protective mechanism from chemotherapy-induced cell death." (PMID 32391256, 2020). "Therefore, we assumed that therapeutic efficacy could be expected with combined treatment using a BCL2 inhibitor, such as ABT-263 (Navitoclax) and ABT-199 (Venetoclax), and an SM (LCL161) in YARS-positive breast cancer." (PMID 33239070, 2020). "For example, in non–small lung carcinoma, melanoma, and breast cancer, NANOG induces autophagy under hypoxia conditions in CSCs by direct regulation of BNIP3, a protein that interacts with Bcl-2 and mediates the disruption of the Bcl-2/Beclin-1 interaction, promoting tumor cell immune resistance." (PMID 33194736, 2020). "This suggests an overrepresentation in the feline species of invasive mammary carcinomas in which the ER pathway is poorly functional, and in which Bcl-2 expression does not proceed from estrogen exposure, but rather from other mechanisms still to be determined." (PMID 30630524, 2019). "In another study involving siRNA knockdown targeting the AKT in MCF-7 human breast cancer cell line, the introduction of the siRNA has reduced the expression of AKT and BCL-2 (anti-apoptotic protein) proteins, which may enhance the probability of cancer cell death." (PMID 31064156, 2019). "Myrrh could kill breast cancer cells without harming healthy cells by inactivating a protein called Bcl-2." (PMID 30906412, 2019). "To determine whether primary breast cancer could be targeted by a therapeutic strategy that reactivates MYC’s apoptotic potential via BH3 mimetics, we assessed the expression of MYC, BCL-2, BCL-XL, and MCL-1 using a tissue microarray (TMA) of 231 primary breast cancer samples." (PMID 30728358, 2019). "While estrogen receptor (ER)-α+ breast cancers express high levels of three anti-apoptotic Bcl-2 family members (Bcl-2, Bcl-xL, and Mcl-1), pharmacological inhibition of Bcl-2 and/or Bcl-xL fails to induce cell death in ERα+ breast cancer cell lines, due to rapid and robust Mcl-1 upregulation." (PMID 31595181, 2019). "Interestingly, western analysis did not reveal a pattern specifically implicating either Bcl-2 or Bcl-xL inhibition as a main driver of Mcl-1 upregulation across all three ER+ breast cancer cell lines tested." (PMID 31595181, 2019). "Moreover, RQ-PCR analysis revealed that the enhanced cytotoxic effect of As2O3 in the presence of melatonin is mediated, at least partly, through suppressing the expression of NF-κB anti-apoptotic target genes such as MCL-1, BCL-2, survivin, XIAP, and c-IAP1 in breast cancer cells." (PMID 31565647, 2018).
breast carcinoma (continued). "We found abundant Mcl-1 expression (but not Bcl-2 or Bcl-xL) upon LTED in cell culture and in vivo, suggesting that Mcl-1, rather than Bcl-2 or Bcl-xL, may be the primary survival factor in AI-resistant ERα+ breast cancers." (PMID 29343814, 2018). "It is also possible that the absence of miR-296-5p could results in increased (or no change in) levels of other anti-apoptotic Bcl-2 proteins that bind to and neutralize the functions of pro-apoptotic proteins in breast cancer." (PMID 29156771, 2017). "On the contrary, the transcript levels of NADH-ubiquinone oxidoreductase chain 3 (ND3), NADH-ubiquinone oxidoreductase chain 5 (ND5) and NADH-ubiquinone oxidoreductase chain 6 (ND6) were not modulated by bcl-2 overexpression in both lung and breast cancer cell lines." (PMID 26866271, 2016). "Therefore, the suppressive effects of Flavipin on Bcl2 and ITGA4 in the examined breast cancer cells could be among the reasons that contributed to the inhibited migration." (PMID 27907195, 2016). "Protein detection showed that, in addition to inhibiting the expression of Ki67 and cyclin D1, UbcH10 RNAi also impaired the increased BCL-2 and MDR-1 expression levels in MCF-7/EPB/TXT cells, which may contribute to abating the drug resistance in the breast cancer cells." (PMID 25739083, 2015). "The clinicopathological role of Bcl-2 in breast cancer was systematically investigated in 634 cases without any adjuvant therapy and 447 cases with tamoxifen monotherapy using full sections from routinely processed archival materials as used in the clinical setting." (PMID 26472348, 2015). "A possible explanation for the lack of effects on BCL2 expression observed in this study could be that docetaxel triggers apoptosis of breast cancer cells through a pathway that does not involve BCL2." (PMID 26487539, 2015). "Additionally, Nar altered the expression of apoptosis and cell-cycle regulatory genes by down-regulating Cdk4, Cdk6, Cdk7, Bcl2, x-IAP and c-IAP-2 and up-regulating p18, p19, p21, caspases 3, 7, 8 and 9, Bak, AIF and Bax in both colorectal and breast cancer cells." (PMID 26074733, 2015). "BCL2 and c-Myc are known to make the negative feedback loop in breast cancer cell line." (PMID 25075970, 2014). "Overexpression of Bcl-2, which is known to block canonical starvation-induced autophagy by binding to Beclin-1, was unable to reverse the non-canonical autophagy triggered by resveratrol in these breast cancer cells." (PMID 25375374, 2014). "Furthermore, deregulation of BCL2, DACH1 and THSD4 may represent key events accompanying GATA3-mediated transformation of normal cells into breast cancer." (PMID 25410484, 2014). "A combination of the analysis of Bcl-2 expression and perhaps other variables (e.g., HER-2, hormone receptor, tumor size and histological subtype) may make it possible, to stratify chemotherapy sensitive subgroup of patients with advanced breast cancer." (PMID 24370277, 2013). "Our analysis of a breast cancer dataset finds that the positive feedback loops across 7 genes, AR, ESR1, MYC, E2F2, PGR, BCL2 and CCND1 are conserved across the basal/triple negative subtypes in multiple datasets that could potentially explain the aggressive nature of this cancer subtype." (PMID 23368093, 2013). "Thus, the results suggest that an up-regulation of bax and the corresponding down-regulation of bcl-2 mRNAs observed in this study may be one of the critical mechanisms through which TAM and/or tranilast induces apoptosis in breast cancer cells." (PMID 24143895, 2013).